IDH1 (isocitrate dehydrogenase (NADP(+)) 1)
Diseases named in the same sentence as IDH1 in open-access papers (continued):
Sharing a sentence is not in itself a finding about the gene and the disease.
glioma (continued). "Mutations in IDH1 mainly affect R132, which is the binding site for isocitrate, and R132H is the most common alteration, comprising >80% of all IDH1 mutations in gliomas." (PMID 31450721, 2019). "In LGG, the ceRNAs shared by MTAP and CDKN2A contained many genes highly associated with gliomas and other cancers, such as IDH1 and CDK4/6." (PMID 31719831, 2019). "IDH1 mutation has been identified in a variety of tumor types, such as glioma, acute myelogenous leukemia, central and periosteal cartilaginous tumors and ICC." (PMID 30849962, 2019). "The survival of all glioma patients with PTPμ high and PTPμ low is plotted either unadjusted or adjusted by gender, grade, age group, and IDH1 mutation status." (PMID 31091655, 2019). "First of all, in accord with in vitro studies, the mitochondrial IDH2 mutations manifested a significantly elevated 2-HG/tCho metabolite ratio compared to gliomas with the cytosolic IDH1 mutation." (PMID 30791611, 2019). "Here we find the unanticipated segregation of both treatment-naïve gliomas as well as recurrent glioblastoma based on IDH1 mutation status within hallmarks of “invasion motility”, “proliferative signaling”, and “inducing angiogenesis”." (PMID 31881020, 2019). "A study showed that transfection of glioma cells with IDH1 mutation leads to the upregulation of HIF1-α and to increased tumor cell proliferation." (PMID 30708988, 2019). "The downregulated genes in IDH1-mut gliomas were associated with immune system processes, and the major Gene Ontology terms were related to chemotaxis and immune cell migration." (PMID 30857299, 2019). "Prognostic estimations have revealed that an IDH1 mutation is associated with an increased survival probability in glioma patients who receive TMZ treatment." (PMID 31906036, 2019). "A clinical study suggested that IDH1 mutation was an independent, favorable prognostic marker in grade 2–4 glioma." (PMID 31578148, 2019). "To address this question, we performed the first epigenetic profiling of single cells in a cohort of 5 gliomas with IDH1 mutation using single nucleus Assay for Transposase-Accessible Chromatin with high-throughput sequencing (snATAC-seq)." (PMID 31806013, 2019). "IDH1 mutation is associated with a good prognosis in patients with glioma but with a worse prognosis in ICC patients." (PMID 30849962, 2019). "Mounting evidence reveals that the immunological tumor microenvironment of the gliomas differs based on their IDH1 mutation." (PMID 31824866, 2019). "Other rare IDH1 variants in codon 132 have been described in gliomas, including R132C, R132S, R132G, and R132L, which show similar effects on IDH1 activity." (PMID 31888244, 2019). "A limitation of this study is that we only tested gliomas for the R132 variant of IDH1, detecting approximately 90% of the IDH‐mutated gliomas." (PMID 30809977, 2019). "All those results support the translational potential of strategies targeting gliomas carrying IDH1 mutations." (PMID 30857299, 2019). "To date, IDH1 mutations have been identified in a number of cancer types, especially in gliomas and acute myelogenous leukemia (AML)." (PMID 31861486, 2019). "Over the last decade the understanding of glioma tumorigenesis was substantially increased due to the discovery of mutations involving the genes encoding isocitrate dehydrogenase 1 and 2 (IDH1/IDH2) enzymes." (PMID 31242696, 2019).
glioma (continued). "The enhanced radiosensitivity and increased cellular stiffness of IDH1R132H-positive glioma cells are consistent with the clinical observation of a less aggressive tumor and a prolonged survival of diffuse glioma patients harboring the IDH1 mutation." (PMID 31242696, 2019). "Based on the intratumoral hypoxia of high-grade gliomas, these observations have important implications for the clinical consequences of an IDH1 mutation in these tumors." (PMID 31242696, 2019). "IDH1/2 mutations are assumed to be one of the earliest genetic alterations and are considered to play a key role in glioma development." (PMID 31888244, 2019). "Similar to ALDOC in glioblastomas, our results showed a significantly inverse correlation between ALDOC and IDH1 mutation status in TCGA glioma cohort (TCGA_GBMLGG, n = 1119)." (PMID 31450822, 2019). "Another recent prominent example of metabolism-associated genes being discovered for functional implication in malignant transformations is the mutation of the isocitrate dehydrogenase 1 and 2 (IDH1/IDH2) in gliomas and acute myeloid leukemia." (PMID 31454887, 2019). "The isocitrate dehydrogenase 1 (IDH1) mutation status is a powerful, independent predictor of glioma-related survival." (PMID 31275753, 2019). "The presence of IDH1 mutation is one of the most important determining factors for molecular diagnosis in the WHO 2016 classification of gliomas." (PMID 30791455, 2019). "According to WHO 2016 update, diffusely infiltrating oligodendroglioma is a slow-growing glioma with IDH1 or IDH2 mutation and codeletion of chromosomal arms 1p and 19q (1p19q-codeletion)." (PMID 31853670, 2019). "To further explore its clinical application, we investigated the relationship between the risk score and glioma subtype, IDH1 and MGMT promoter status, respectively." (PMID 31379707, 2019). "In gliomas and malignancies, IDH1 mutations induce postmenopausal changes and promote tumorigenesis." (PMID 31729414, 2019). "Preclinical data have shown a dramatic anti-tumor effect of hypomethylating drugs, such as 5-azacytidine, on IDH1-mutated human gliomas." (PMID 31263678, 2019). "The largest community in LGG contained 798 nodes, including some glioma-associated genes like IDH1 and CDK4/6, in which most ceRNA pairs were driven by copy number deletion." (PMID 31719831, 2019). "In clinical samples of gliomas with IDH1 mutation, levels of D-2-hydroxyglutarate (D-2HG) were increased significantly compared with gliomas without IDH mutation." (PMID 31278288, 2019). "The captation significantly correlated with IDH1 mutation status in the majority of gliomas, with the exception of glioblastomas." (PMID 31737567, 2019). "Glioma patients with IDH1 mutations have a longer overall survival and show a better response to treatment; the reasons for this are still unclear." (PMID 31888244, 2019). "ATRX deficiency almost invariably co-occurs with mutations in IDH1 or its homologue IDH2 in adult gliomas." (PMID 30808951, 2019). "Further investigation is urgently required to clarify the association between miR-708 and IDH1 mutations in glioma." (PMID 31171769, 2019). "Since the IDH1 R132H mutation is more common in gliomas, more clinical trials have been conducted for IDH1." (PMID 31263678, 2019). "Results after vaccination indicated that neopeptide vaccine lead to effective mutation-specific antitumor immune responses in the mouse model with IDH1 (R132H)-mutated gliomas." (PMID 31492199, 2019). "Noninvasive preoperative assessment of the genetic subtypes of the IDH1 mutation in glioma patients is likely to enable more effective selection of clinical treatment options." (PMID 31275753, 2019).
glioma (continued). "Inhibitors of mutated IDH1/2 enzymes entered clinical trials and represent a novel drug class for targeted therapy of gliomas." (PMID 30857299, 2019). "Further studies of gene expression profiling in IDH1 mutation gliomas using NGS will provide more genetic information and will lead to new treatments for this refractory disease." (PMID 31443404, 2019). "Overall, these findings demonstrate that PPM1D mutations drive a unique pattern of global DNA methylation, distinct from that found in IDH1 mutant gliomas, which is associated with CpG island hypermethylation and NAPRT gene silencing." (PMID 31439867, 2019). "Subsequent studies identified mutations in either IDH1 or IDH2 in over 70% of lower-grade gliomas, as well as a small subset (~5%) of secondary glioblastomas that evolved from lower-grade precursors." (PMID 31788444, 2019). "Forexample, partial efficacy of selective inhibitors of isocitrate dehydrogenasewith the IDH1 R132H mutation has been shown both invitro and in glioma models." (PMID 31413876, 2019). "Studies have identified that somatic heterozygous mutations in IDH1/2 play a crucial role in the development of cancers, including glioma and leukemia." (PMID 29661250, 2018). "Conflicting reports exist regarding the influence of IDH1 mutation on overall 5hmC abundance in gliomas." (PMID 29428975, 2018). "Mutations in IDH1 are observed in a number of tumor types, including the majority of low-grade gliomas and secondary glioblastomas." (PMID 29562167, 2018). "The World Health Organization (WHO) revised the low(er) grade glioma (LGG) classification system in 2016 to include isocitrate dehydrogenase (IDH1/2) mutations and 1p/19q co-deletion status in addition to glioma grade and histology." (PMID 30647847, 2018). "In recent years, de novo missense structural mutations in the IDH1 gene of arginine at site 132 (R132) have become a standard for diagnostication and prognostication in glioma management." (PMID 29303363, 2018). "Another approach to determine the metabolic effect of the IDH1 mutation on glioma cells is to inhibit the IDH1 mutation in an endogenous IDH1 mutant line." (PMID 29692895, 2018). "IDH1 mutated high grade gliomas arise from lower-grade glioma (secondary GBM) and shows specific radiographic, histologic and transcriptional features consistent with a less aggressive prognosis." (PMID 30327965, 2018). "Proneural subtype, isocitrate dehydrogenase 1 (IDH1) mutations, and epileptic seizures are closely associated suggesting that aberrant neuronal differentiation contributes to glioma-associated seizures." (PMID 30297697, 2018). "We demonstrate a feasible radiopharmacodynamics approach to support the rapid clinical translation of rationally designed drugs targeting IDH1/2 mutations for personalized and precision medicine of glioma patients." (PMID 29662077, 2018). "The specific gene expression changes associated with this glioma hypermethylated phenotype in IDH1/2 mutant gliomas are yet to be elucidated." (PMID 30647847, 2018). "For instance, a study using a cohort of 60 patients with gliomas with IDH1–R132H mutation was performed to understand if the GAMs samples also have the IDH1–R132H mutation." (PMID 30123112, 2018). "Therapeutic sensitivity is important to improved survival of glioma patients with IDH1 mutations, but mutant IDH1 inhibitors desensitized tumors cells to irradiation and chemotherapy." (PMID 30416682, 2018). "In secondary glioblastomas IDH-1 (R132H) mutated glioma cells were completely devoid of the EMT transcription factors SLUG and TWIST while vascular proliferations were constantly positive for those factors." (PMID 29844871, 2018). "First passage glioma cells from tumours with IDH1 R132H mutations showed a more restricted differentiation pattern as compared to wildtype gliomas and almost exclusively expressed markers of oligodendrocytes and neurons." (PMID 30297697, 2018).
glioma (continued). "Using an automatic clustering of TAC, we aimed at investigating the association between dynamic 18F-FET PET findings of whole-tumor voxels, IDH1 mutation status and survival in patients with gliomas." (PMID 29953478, 2018). "We then specifically focused on evaluating the potential consequence of the IDH1 mutation and its impact on the immune landscape in gliomas." (PMID 29643764, 2018). "The effects of the most frequent IDH1 mutation (R132H) of gliomas in energy metabolism and substrate consumption were studied in an IDH1 mutation (R132H) carrying glioma model (isogenic pair: U251 wt and its genetically engineered counterpart - U251 IDH1m)." (PMID 30404651, 2018). "Gliomas harboring the IDH1-R132H mutation demonstrated altered phospholipid metabolism characterized by decreased phosphoethanolamine levels and increased glycerophosphocholine levels." (PMID 30283018, 2018). "As it will be discussed in the section on the molecular abnormalities of the WHO grade II/III gliomas, the IDH1 mutations are much more frequent in these tumors than in glioblastomas." (PMID 30279357, 2018). "Accordingly, IDH1/2 wildtype gliomas are categorized as glioblastoma (formerly primary glioblastoma) and IDH1/2-mutated gliomas (including formerly classified secondary glioblastoma) as astrocytic glioma and oligodendroglioma." (PMID 30274242, 2018). "While IDH1 mutations are more common in gliomas (80%) and AML (20%), IDH2 mutations occur more frequently in AML (20%) and cholangiosarcomas (20%)." (PMID 30405699, 2018). "The gene encoding isocitrate dehydrogenase 1 (IDH1) is frequently mutated in several tumor types including gliomas." (PMID 29953513, 2018). "In conclusion, based on dynamic 18F-FET PET acquisition, we developed a full automatic clustering approach of TAC which appears to be a valuable noninvasive diagnostic (for IDH1 mutant status) and prognostic marker in patients with gliomas." (PMID 29953478, 2018). "Neomorphic mutations in IDH1, mostly occurring at arginine 132, are frequently found in several human cancer types, including glioma, acute myeloid leukemia (AML), and myeloproliferative neoplasm." (PMID 29596354, 2018). "Isocitrate dehydrogenase 1 (IDH1) mutations in gliomas, fibrosarcoma, and other cancers leads to a novel metabolite, D-2-hydroxyglutarate, which is proposed to cause tumorigenesis." (PMID 30597885, 2018). "The majority of lower grade glioma possess an activating mutation in a metabolic gene called isocitrate dehydrogenase I (IDH1)." (PMID 30597885, 2018). "5-Hydroxymethylcytosine (5hmC) is implicated in glioma pathogenesis; however, its role in IDH1 mutant gliomas is incompletely understood." (PMID 29428975, 2018). "The authors suggested that the risk of VTE in IDH1 mutant glioma patients is reduced by the inhibitory effect of D‐2‐HG on platelet aggregation." (PMID 29676036, 2018). "IDH1/2 mutations are also present in approximately 80% of grade II-III gliomas (Cohen, Holmen & Colman, 2013), producing a CpG island hypermethylator phenotype." (PMID 29922517, 2018). "Specific IDH1 mutations lead to discriminable protein profiles for low-grade glioma (sdis = − 0.47; p = 0.0; srand = − 3.1e−6) and glioblastoma (sdis = − 1.59; p = 5.0e−4; srand = − 1.0e−5)." (PMID 30442178, 2018). "Clinically, patients with mutations in IDH1/2 are found to survive longer compared to patients with “wild-type” gliomas." (PMID 30192797, 2018). "IDH1 mutation in glioma results in a gain of function, producing the oncometabolite 2-hydroxyglutarate (2-HG)." (PMID 29428975, 2018). "Loss of heterozygosity (LOH) at the IDH1 locus in gliomas and leukemias, as well as monoallelic expression of IDH1 in gliomas, are well known." (PMID 29439493, 2018).
glioma (continued). "Since the discovery of mutations in IDH1 in gliomas and other tumors, significant strides have been made to better understand the downstream consequences of this oncogenic mutation." (PMID 29562167, 2018). "These compounds were shown to decrease cellular D-2HG levels, reduce histone methylation, suppress proliferation of stem-like cancer cells in BT142 glioma with IDH1 R132H mutation." (PMID 29439493, 2018). "The heterozygous R132H mutation in IDH1 accounts for 95% of IDH1/2 mutations in gliomas, however heterozygous mutations also occur in the analogous amino acid of IDH2 (R172), including R172G, R172K, and R172M." (PMID 30647847, 2018). "In gliomas, IDH1 mutations are one of the earliest genetic changes identified, preceding other common genetic aberrations such as 1p19q co-deletion, and are therefore present in virtually all tumor cells." (PMID 29953513, 2018). "Conversely, IDH1/2 mutations, which are frequently present in diffusely infiltrating gliomas, rarely occur in PXAs29." (PMID 30250216, 2018). "IDH1 mutation-mediated inhibition of TET proteins is one mechanism altering the DNA methylation landscape in G-CIMP gliomas." (PMID 29428975, 2018). "Expression of genes involved in the immune response was positively related to glioma grades but negatively associated with IDH1 mutation and MGMT promoter methylation." (PMID 29764444, 2018). "Recently, many studies showed that IDH1 is mutated in various human cancers, especially in low-grade glioma." (PMID 30153799, 2018). "As a result, the WHO classification for central nervous system tumors was recently modified to include mutations in IDH1/IDH2 as a critical part of the diagnosis of infiltrating gliomas." (PMID 30170631, 2018). "This IDH1 R132H mutation is prevalent in several forms of human cancer, such as low-grade gliomas and secondary glioblastomas." (PMID 29320744, 2018). "As we continue to develop a more comprehensive understanding of phenotypic variation between the different IDH1 mutations in glioma, this potential of subtype stratification by substituting AA will be realized." (PMID 29303363, 2018). "The presence of an isocitrate dehydrogenase (IDH1/2) mutation in gliomas is associated with favorable outcomes compared to gliomas without the mutation (IDH1/2 wild-type, WT)." (PMID 30647847, 2018). "IDH1 mutations occur somatically in >70% in grade II–III gliomas and secondary GBMs, and 8.5% of AML cases." (PMID 29439493, 2018). "The role of IDH1 gene mutation in esophageal squamous cell carcinoma, glioma and acute myeloid leukemia (AML) have been successively reported." (PMID 30153799, 2018). "The univariate analysis showed that age, IDH-1, and hematological factors were all significantly associated with overall survival (OS) in patients with gliomas." (PMID 30154718, 2018). "Then, aim was to develop a full automatic clustering approach of TAC from dynamic 18F-FET PET and evaluate its association with IDH1 mutation status and survival in patients with gliomas." (PMID 29953478, 2018). "In a prospective cohort study, intratumoral IDH1 R132H mutation and podoplanin were determined in brain tumor specimens (mainly glioma) by immunohistochemistry." (PMID 29676036, 2018). "In gliomas and several hematologic malignancies, somatic IDH1 and IDH2 mutations have been associated with a characteristic DNA hypermethylation phenotype." (PMID 30200539, 2018). "The analysis of paired tumor samples has allowed us to better understand the mechanism underlying the progression of low-grade gliomas, with mutations in IDH1, into high-grade gliomas." (PMID 30279357, 2018).